MYBL1 (MYB proto-oncogene like 1)
Description:
Transcription factor that specifically recognizes the sequence 5'-YAAC[GT]G-3'. Acts as a master regulator of male meiosis by promoting expression of piRNAs: activates expression of both piRNA precursor RNAs and expression of protein-coding genes involved in piRNA metabolism (By similarity). The piRNA metabolic process mediates the repression of transposable elements during meiosis by forming complexes composed of piRNAs and Piwi proteins and governs the methylation and subsequent repression of transposons, which is essential for the germline integrity (By similarity). Transcriptional activator of SOX30 (By similarity).
Synonyms: A-Myb; AMYB
Tractability: PROTAC: UniProt records ubiquitination sites on it; ubiquitination databases record sites on it.
Gene: Protein-coding gene on chromosome 8 (66,562,175 to 66,614,247, reverse strand). Ensembl gene ENSG00000185697.
Subcellular location: Nucleus
Subcellular location (Human Protein Atlas): Nucleoplasm
Pathways (Reactome):
Gene expression (Transcription): PIWI-interacting RNA (piRNA) biogenesis
Gene Ontology:
Molecular function: DNA-binding transcription activator activity, RNA polymerase II-specific; RNA polymerase II cis-regulatory region sequence-specific DNA binding
Biological process: positive regulation of transcription by RNA polymerase II; male meiosis I; mitotic cell cycle; positive regulation of DNA-templated transcription; positive regulation of piRNA transcription; spermatogenesis; regulation of DNA-templated transcription
Cellular component: nucleoplasm; nucleus
Genetic constraint (gnomAD): Loss-of-function variants: 4 observed, 32.65 expected, observed/expected ratio (o/e) 0.12, 90% interval 0.059 to 0.28. The upper end of that interval is the gene's LOEUF score, 0.28, which puts it in group 1 of 6, group 1 being the genes least tolerant of losing a copy. Missense variants: 399 observed, 485.01 expected, observed/expected ratio (o/e) 0.82, 90% interval 0.76 to 0.89. Synonymous variants: 154 observed, 168.7 expected, observed/expected ratio (o/e) 0.91, 90% interval 0.8 to 1.04.
Homologues: Orthologues: chimpanzee MYBL1 (99% identical), macaque MYBL1 (99% identical), rabbit MYBL1 (94% identical), dog MYBL1 (94% identical), pig MYBL1 (94% identical), mouse Mybl1 (92% identical), guinea pig MYBL1 (92% identical), rat Mybl1 (91% identical), zebrafish mybl1 (53% identical), Drosophila melanogaster Myb (28% identical), zebrafish mybl2a (22% identical). Paralogues in human: MYB (45% identical), MYBL2 (37% identical), CDC5L (18% identical), SNAPC4 (18% identical), DMTF1 (14% identical), TTF1 (9% identical).
Diseases named in the same sentence as MYBL1 in open-access papers:
MYBL1 is named in the same sentence as 94 diseases in open-access papers, as found by Europe PMC text mining. Sharing a sentence is not in itself a finding about the gene and the disease. The quoted sentences say what the papers report.
diffuse astrocytoma (41 papers, 2016 to 2025). A low-grade (WHO grade II) astrocytic neoplasm. "MYB or MYBL1 alterations represent driver mutations that occur early in the tumorigenesis process of diffuse astrocytoma, MYB or MYBL1-altered, resulting in the presence of this abnormality in nearly all tumor cells." (PMID 40668344, 2025). "The MYB/MYBL1 alterations are associated with diffuse astrocytoma, while the MYB-QKI fusion is highly relevant to AG." (PMID 37920791, 2023). "MYBL1 has been recently shown to be implicated in the oncogenesis of diffuse astrocytoma, which were discovered to harbor recurrent rearrangements in chromosome 8q, resulting in tandem duplication/truncation of the MYBL1 gene." (PMID 27533466, 2016). "“MYB- or MYBL1-altered diffuse astrocytoma” is a rare entity defined by a canonical fusion event of MYB- or MYB1L, with the most common partner genes PCDHGA1, MMP16, and MAML2." (PMID 40392954, 2025). "Angiocentric glioma and diffuse astrocytoma MYB/MYBL1 altered tumors show overlapping histopathological features and both express MYB gene involvement." (PMID 39440342, 2024). "Just like diffuse astrocytomas with MYB or MYBL1 alteration, angiocentric gliomas infiltrate adjacent brain structures diffusely, although they can appear as well-demarcated lesions in MRI." (PMID 36941392, 2023). "Diffuse astrocytoma with alterations of MYB/MYBL1 is a diffuse, infiltrating tumor composed of astrocytic cells." (PMID 37920791, 2023). "In 2021, the World Health Organization updated their CNS tumor classification to include two categories of these pLGGs: angiocentric glioma with MYB-QKI fusions and diffuse astrocytoma with various MYB/MYBL1 alterations." (PMID 38137148, 2023). "The molecular alterations of these “pediatric-type” grade II diffuse astrocytomas were recently described and concerned the BRAF p.V600E mutation, FGFR1 alterations or MYB or MYBL1 rearrangement." (PMID 32771057, 2020). "Originally described in Ramkissoon et. al. in 28% (5/18) of diffuse astrocytomas, these MYBL1-driven tumors showed a partial duplication with truncation of its C-terminal regulatory." (PMID 32164789, 2020). "Notably, 5 of 6 patients with altered KMT5B in our study had the same mutation of p.Glu833_Asp835delinsSerProSer, including 3 diffuse astrocytomas, MYB- or MYBL1-altered and 2 diffuse pediatric-type high-grade gliomas, H3-wildtype and IDH-wildtype." (PMID 37214395, 2023). "The spectrum of long-term low-grade epilepsy-associated brain tumors is expanding rapidly and, in addition to DNTs, includes diffuse astrocytoma MYB or MYBL1-altered polymorphous low-grade neuroepithelial tumor of the young (PLNTY), diffuse low-grade glioma, MAPK pathway-altered tumor, and so on." (PMID 37525202, 2023). "The prognosis of diffuse astrocytoma with alterations of MYB/MYBL1 is generally excellent." (PMID 37920791, 2023). "More recent reports of MYBL1 alterations in pLGG suggest MYBL1 alterations may be even rarer, being found in 2/17 (12%), 7/50 (14%), and 1/17 (6%) diffuse astrocytomas." (PMID 32164789, 2020). "Diffuse astrocytoma, MYB- or MYBL1-altered, is classified as CNS WHO grade 1 with favorable prognosis, with a reported 5-year event-free survival rate of 100% in cases with near-total resection." (PMID 40668344, 2025). "There is a trend toward collectively managing AG and diffuse astrocytoma, MYB- or MYBL1-alterations within the same spectrum, under the broader classification of MYB- or MYBL1-altered pLGGs." (PMID 40668344, 2025). "Diffuse astrocytoma, MYB- or MYBL1-altered is an infiltrative neoplasm of astroglial origin, characterized by uniform cellular morphology and specific genetic modifications in either the MYB or MYBL1 genes." (PMID 40668344, 2025). "This histological overlap between AG and diffuse astrocytoma, MYB- or MYBL1-altered pose challenge in differential diagnosis." (PMID 40668344, 2025).
diffuse astrocytoma (continued). "Diffuse astrocytoma, MYB- or MYBL1-altered, is a diffusely infiltrative astrocytic neoplasm that lacks histomorphological features indicative of an anaplastic nature." (PMID 40861626, 2025). "Both diffuse astrocytoma, MYB- or MYBL1-altered and angiocentric glioma (AG) are pLGGs that harbor MYB or MYBL1 alterations." (PMID 40668344, 2025). "The primary therapeutic approach for diffuse astrocytoma, MYB- or MYBL1-altered, is maximal safe surgical resection." (PMID 40668344, 2025). "Diffuse astrocytoma, MYB- or MYBL1-altered, CNS WHO grade 1, is a newly recognized tumor entity in the 2021 World Health Organization classification of central nervous system tumors." (PMID 40861626, 2025). "In most cases of diffuse astrocytoma, MYB- or MYBL1-altered form masses in the supratentorial region, although brainstem involvement occurs only exceptionally." (PMID 40668344, 2025). "The DNA methylation profile of this tumor closely aligns with that of diffuse astrocytoma, MYB- or MYBL1-altered." (PMID 40861626, 2025). "Two morphological subtypes are recognised: angiocentric glioma and diffuse astrocytoma, MYB- or MYBL1-altered." (PMID 39294363, 2024). "Conversely, Diffuse astrocytoma, MYB- or MYBL1-altered tumors show structural variations that result in a fusion involving more commonly MYBL1, although MYB alterations also occur." (PMID 39422766, 2024). "This category includes the following tumors: diffuse astrocytoma, MYB/MYBL1 altered, angiocentric glioma, polymorphous low-grade neuroepithelial tumor of the young (PLNTY), and diffuse low-grade glioma, mitogen-activated protein kinase (MAPK) pathway altered." (PMID 39440342, 2024). "IHC: Similar to diffuse astrocytoma, MYB/MYBL1 altered, along with a few cases showing focal epithelial membrane antigen (EMA) positivity in a dot-like pattern representing epithelioid elements." (PMID 39440342, 2024). "Diffuse astrocytoma, altered by MYB/MYBL1 (MYB proto-oncogene like 1), is a cerebral tumor predominantly located in the cortical or subcortical areas." (PMID 39440342, 2024). "Diffuse astrocytoma, MYB- or MYBL1-altered is rare, accounting for only 2% of pediatric low-grade gliomas." (PMID 38544524, 2024). "Histologically, diffuse astrocytoma, MYB- or MYBL1-altered typically shows low-to-moderate cellularity and is composed of well-differentiated neoplastic astrocytes with small, round-to-ovoid nuclei, diffusely permeating neuropil." (PMID 38544524, 2024). "Diffuse astrocytoma, MYB/MYBL1 altered, and angiocentric glioma are classified as WHO grade 1 tumors." (PMID 39440342, 2024). "Diffuse astrocytoma, MYB- or MYBL1-altered shows a benign clinical behavior, even though the available outcome data are limited due to its rarity." (PMID 38544524, 2024). "A final diagnosis of angiocentric glioma was reached in 6 cases, and the remaining 8 cases were diagnosed as diffuse astrocytoma, MYB- or MYBL1-altered." (PMID 39422766, 2024). "Among CNS tumors, MYB or MYBL1 alterations are noted in the current World Health Organization (WHO) classification as 2 tumor types: “Angiocentric glioma” and “Diffuse astrocytoma, MYB- or MYBL1-altered,” both as WHO grade 1." (PMID 39422766, 2024). "pLGGs include diffuse astrocytoma, MYB- or MYBL1-altered; angiocentric glioma; polymorphous low-grade neuroepithelial tumor of the young; and diffuse low-grade glioma, MAPK pathway-altered." (PMID 37214395, 2023). "In contrast, fewer patients (3/6, 50%) with diffuse astrocytoma, MYB- or MYBL1-altered, showed enhancement." (PMID 37214395, 2023). "The mean maximum tumor diameter was 4.19, 4.96, and 4.17 cm for diffuse astrocytoma, MYB- or MYBL1-altered, diffuse midline glioma, H3 K27-altered, and diffuse pediatric-type high-grade glioma, H3-wildtype and IDH-wildtype, respectively." (PMID 37214395, 2023).
diffuse astrocytoma (continued). "In diffuse astrocytoma, MYB- or MYBL1 altered, large cysts are commonly reported, however, in our study, cyst was only observed in one case, albeit with the largest cyst diameter among all samples." (PMID 37214395, 2023). "Especially in adolescents and young adults, diffuse astrocytomas, MYB-altered or MYBL1-altered, have to be distinguished from IDH-wildtype and IDH-mutated diffuse gliomas." (PMID 37462746, 2023). "Diffuse astrocytomas are low-grade diffusely growing neoplasms, MYB-altered or MYBL1-altered, and commonly arise within the cortex or subcortex of the temporal and frontal lobes." (PMID 37462746, 2023). "Patients with diffuse astrocytoma, MYB- or MYBL1-altered are mostly diagnosed with drug-resistant seizures, previous study suggested that 81% of these patients develop epilepsy in childhood and the median age of seizure onset is 10 years." (PMID 37214395, 2023). "DNA methylation array profiled the tumour as "methylation class diffuse astrocytoma, MYB or MYBL1-altered subtype B (infratentorial)" and an in-frame MYB::QKI fusion was identified by RNA sequencing, confirming the diagnosis of angiocentric glioma." (PMID 37362245, 2023). "The remaining IDH-wildtype anaplastic astrocytomas (13/39) and IDH-wildtype diffuse astrocytomas (7/26) were reclassified as pediatric-type diffuse astrocytoma, MYB- or MYBL1-altered or high-grade diffuse glioma, H3- and IDH-wildtype." (PMID 36998447, 2023). "Two newly defined CNS WHO grade 1 entities in this category are diffuse astrocytoma, MYB- or MYBL1-altered, and polymorphous low-grade neuroepithelial tumor of the young (PLNTY)." (PMID 36617415, 2023). "Both diffuse astrocytoma, MYB- or MYBL1-altered, and diffuse low-grade glioma, MAPK pathway-altered, display nonspecific histological features characteristic of low-grade glial tumors and necessitate molecular characterization." (PMID 38157879, 2023). "Diffuse astrocytoma, MYB- or MYBL1-altered, is a diffuse infiltrative neoplasm composed of astrocytoid cells that exhibit histological morphology indistinguishable from conventional astrocytomas." (PMID 37920791, 2023). "Diffuse astrocytoma, MYB- or MYBL1-altered accounts for approximately 2% of all pediatric low-grade gliomas composed of monomorphic cells." (PMID 37214395, 2023). "Under “pediatric type diffuse low-grade gliomas,” three new tumor types are introduced: “diffuse astrocytoma, MYB or MYBL1-altered”; “polymorphous low-grade neuroepithelial tumor of the young (PLNTY)”; and “diffuse low-grade glioma-MAPK altered”." (PMID 38137148, 2023). "In contrast, the mOS of diffuse astrocytoma, MYB- or MYBL1-altered, was 46.3 months, suggesting that adult patients with high-grade pediatric-type diffuse glioma are less likely to experience longer survival and better prognosis." (PMID 37214395, 2023). "Then, there are three subclasses of diffuse astrocytoma, MYB or MYBL1-altered, whose methylation profiles are most similar to paediatric MYB/MYBL1-altered diffuse astrocytomas and angiocentric gliomas." (PMID 36428772, 2022). "Contrarily to specific forms, “non‐specific/diffuse DNTs” corresponded to a heterogeneous molecular group encompassing newly described distinct histo‐molecular tumours as PLNTY or diffuse astrocytoma, MYB or MYBL1‐altered." (PMID 35836307, 2022). "Based on histomorphology and molecular profile, we detected a diffuse astrocytoma, MYB or MYBL1-altered with MYBL1:MMP16-fusion." (PMID 35727368, 2022). "The “non‐specific/diffuse DNTs” subgroup encompasses various recently described histomolecular entities, such as PLNTY and diffuse astrocytoma, MYB or MYBL1 altered." (PMID 35836307, 2022). "For example, diffuse astrocytoma, MYB- or MYBL1-altered belong to the family of pediatric-type diffuse low-grade gliomas and are classified as CNS WHO grade 1." (PMID 36425564, 2022).
diffuse astrocytoma (continued). "In cases where such genetic alterations are not detectable, a distinct DNA methylation profile characteristic of diffuse astrocytoma, MYB- or MYBL1-altered, may be sufficient to establish the diagnosis." (PMID 40861626, 2025). "According to the new WHO CNS5 classification, 4 tumor types have been identified: (i) diffuse astrocytoma, MYB- or MYBL1-altered; (ii) angiocentric glioma; (iii) polymorphic neuroepithelial tumor of the young; (iv) diffuse low-grade, mitogen-activated protein kinase (MAPK) pathway-altered glioma." (PMID 41050069, 2025). "Diffuse astrocytoma, MYB- or MYBL1-altered is a diffusely infiltrative astroglial neoplasm composed of monomorphic cells and characterized by genetic alterations regarding MYB or MYBL1 genes." (PMID 38544524, 2024). "MYB alterations are in common with diffuse astrocytoma, MYB- or MYBL1-altered, which represents the closer differential diagnosis and, in rare cases, may also harbor the hallmark fusion of angiocentric glioma." (PMID 38544524, 2024). "After removing missing data, 6 patients with diffuse astrocytoma, MYB- or MYBL1-altered, 1 with diffuse midline glioma, H3 K27-altered, and 7 with diffuse pediatric-type high-grade glioma, H3-wildtype and IDH-wildtype were included in the analysis, and representative radiological images are shown." (PMID 37214395, 2023). "Among 596 adult patients, 20 patients with pediatric-type glioma were screened, including 6 with diffuse astrocytoma, MYB- or MYBL1-altered, 2 with diffuse midline glioma, H3 K27-altered, and 12 with diffuse pediatric-type high-grade glioma, H3-wildtype and IDH-wildtype." (PMID 37214395, 2023). "Diffuse astrocytoma, MYB or MYBL1-altered, shows astrocytic cells in a fine bubbly neuropil." (PMID 37525202, 2023). "These include diffuse astrocytoma, MYB- or MYBL1-altered; diffuse low-grade glioma, MAPK pathway-altered; polymorphous low-grade neuroepithelial tumor of the young (BRAF mutations and FGFR2 fusions); and infant-type hemispheric glioma (alterations in NTRK, ROS1, ALK, or MET)." (PMID 37509316, 2023). "pDLGG includes four tumor types, namely, diffuse astrocytoma, MYB- or MYBL1-altered; angiocentric glioma; polymorphous low-grade neuroepithelial tumor of the young (PLNTY); and diffuse low-grade glioma, MAPK pathway-altered, three types of which are newly recognized tumor types." (PMID 37920791, 2023). "In this study, we described and analyzed adult patients with pediatric-type diffuse gliomas, particularly diffuse astrocytoma, MYB- or MYBL1-altered, diffuse midline glioma, H3 K27-altered, and diffuse pediatric-type high-grade glioma, H3-wildtype and IDH-wildtype." (PMID 37214395, 2023). "Interestingly, 77% of IDGs demonstrated MYM/MYBL1 alterations, and all (100%) were IDH-wild-type, which are closely related to pediatric MYB/MYBL1-altered diffuse astrocytomas, according to the WHO fifth edition of CNS tumor classification." (PMID 36699536, 2022). "Therefore, WHO CNS5 introduced a new type of glioma called diffuse astrocytoma, MYB- or MYBL1-altered belonging to the family of pediatric-type diffuse low-grade gliomas." (PMID 34638714, 2021). "FGFR1, NTRK2, MYB, and MYBL1 rearrangements: Among patients with diffuse astrocytomas who had testing for rearrangements of FGFR1 (n = 5), NTRK2 (n = 4), MYB (n = 2), or MYBL1 (n = 1) performed on both paired surgical specimens, results remained negative in all pairs, with no acquisition or loss." (PMID 33153497, 2020). "Consequently, the distinction of angiocentric gliomas from what the WHO terms "diffuse astrocytomas, MYB/MYBL1-altered" could be revisited at the time of the next revision of the CNS WHO classification." (PMID 39422766, 2024). "Moreover, WHO CNS5 classifies diffuse astrocytomas, MYB- or MYBL1-altered as CNS WHO grade 1." (PMID 34638714, 2021). "Unlike other pediatric low-grade gliomas (pLGGs), diffuse astrocytoma, MYB- or MYBL1-altered, typically lacks common therapeutic targets such as BRAF mutations." (PMID 40668344, 2025).
diffuse astrocytoma (continued). "No MYB or MYBL1 rearrangements were identified in any of the cases, suggesting that gangliogliomas are genetically distinct from the majority of angiocentric gliomas and pediatric IDH-wildtype diffuse astrocytomas." (PMID 29880043, 2018).